ENSG00000283563 (novel protein)
Gene: Protein-coding gene on chromosome 3 (28,349,178 to 29,767,537, forward strand). Ensembl gene ENSG00000283563.
Genetic constraint (gnomAD): Missense variants: 231 observed, 221.66 expected, observed/expected ratio (o/e) 1.04, 90% interval 0.94 to 1.16. Synonymous variants: 74 observed, 75.72 expected, observed/expected ratio (o/e) 0.98, 90% interval 0.81 to 1.19.